ZNF16 (zinc finger protein 16)
Description:
Acts as a transcriptional activator. Promotes cell proliferation by facilitating the cell cycle phase transition from the S to G2/M phase. Involved in both the hemin- and phorbol myristate acetate (PMA)-induced erythroid and megakaryocytic differentiation, respectively. Also plays a role as an inhibitor of cell apoptosis.
Synonyms: HZF1; KOX9
Tractability: PROTAC: UniProt records ubiquitination sites on it; ubiquitination databases record sites on it.
Gene: Protein-coding gene on chromosome 8 (144,930,358 to 144,950,888, reverse strand). Ensembl gene ENSG00000170631.
Subcellular location: Nucleus
Subcellular location (Human Protein Atlas): Nucleoli; Nucleoplasm
Gene Ontology:
Molecular function: protein binding; DNA-binding transcription factor activity, RNA polymerase II-specific; RNA polymerase II cis-regulatory region sequence-specific DNA binding
Biological process: cellular response to sodium dodecyl sulfate; negative regulation of apoptotic process; positive regulation of cell cycle phase transition; positive regulation of cell population proliferation; positive regulation of erythrocyte differentiation; positive regulation of kinase activity; positive regulation of megakaryocyte differentiation; regulation of transcription by RNA polymerase II
Cellular component: nucleolus; nucleoplasm; nucleus
Genetic constraint (gnomAD): Loss-of-function variants: 14 observed, 18.99 expected, observed/expected ratio (o/e) 0.74, 90% interval 0.49 to 1.15. The upper end of that interval is the gene's LOEUF score, 1.15, which puts it in group 5 of 6, group 1 being the genes least tolerant of losing a copy. Missense variants: 830 observed, 886.63 expected, observed/expected ratio (o/e) 0.94, 90% interval 0.88 to 0.99. Synonymous variants: 312 observed, 314.73 expected, observed/expected ratio (o/e) 0.99, 90% interval 0.9 to 1.09.
Homologues: Orthologues: macaque ZNF16 (95% identical), chimpanzee ZNF16 (91% identical), rabbit ZNF16 (72% identical), pig ZNF16 (59% identical). Paralogues in human: ZNF484 (42% identical), ZNF585B (42% identical), ZNF658 (41% identical), ZNF132 (41% identical), ZNF33B (40% identical), ZNF568 (40% identical), ZNF41 (40% identical), ZNF585A (40% identical), ZNF605 (39% identical), ZNF470 (39% identical), ZNF182 (39% identical), ZNF197 (39% identical), and 164 more.
Diseases named in the same sentence as ZNF16 in open-access papers:
ZNF16 is named in the same sentence as 24 diseases in open-access papers, as found by Europe PMC text mining. Sharing a sentence is not in itself a finding about the gene and the disease. The quoted sentences say what the papers report.
gallbladder carcinoma (2 papers, 2020 to 2026). "ZNF16 expression was positively associated with histological grade, shorter survival, and increased risk of relapse in gallbladder carcinoma patients." (PMID 41467516, 2026). "Given that ZNF16 expression and mutations have been associated with gallbladder carcinoma and tongue squamous cell carcinoma, we next explored differentially expressed genes that are related to cancer processes." (PMID 41467516, 2026). "Patients with cytoplasmic ZNF16 positive carcinomas had a 1.675-fold (95% CI; 1.038–2.703) greater risk of death from gallbladder carcinoma." (PMID 32460791, 2020). "In conclusion, we present that the expression of FAM83H and ZNF16 are closely associated, and that high expression patterns of these proteins are significantly associated with shorter survival of gallbladder carcinoma patients." (PMID 32460791, 2020). "In univariate analysis, nuclear and cytoplasmic expression of FAM83H or ZNF16 were significantly associated with shorter survival of gallbladder carcinoma patients." (PMID 32460791, 2020). "Another interesting finding of our study is that the expression of FAM83H and ZNF16 were closely associated with each other in gallbladder cancers." (PMID 32460791, 2020). "This study suggests FAM83H and ZNF16 are associated with the progression of gallbladder carcinoma, and the expressions of FAM83H and ZNF16 might be novel prognostic indicators of gallbladder carcinoma patients." (PMID 32460791, 2020). "Moreover, the positivity for the expression of nuclear FAM83H, cytoplasmic FAM83H, nuclear ZNF16, and cytoplasmic ZNF16 were significantly associated with shorter survival of gallbladder carcinoma patients." (PMID 32460791, 2020). "Moreover, the expression of nuclear FAM83H, cytoplasmic FAM83H, nuclear ZNF16, and cytoplasmic ZNF16 were associated with the survival of gallbladder carcinoma patients." (PMID 32460791, 2020). "Patients with nuclear ZNF16 positive carcinomas had a 3.287-fold (95% CI; 1.888–5.722) greater risk of death and a 3.038-fold (95% CI; 1.765–5.229) greater risk of relapse or death from gallbladder carcinoma." (PMID 32460791, 2020). "Moreover, the individual and co-expression patterns of nuclear FAM83H and ZNF16 were significantly associated with the prognosis of gallbladder carcinoma patients who received adjuvant chemotherapy." (PMID 32460791, 2020). "When considering the prognostic significance of the expression of FAM83H and ZNF16 in gallbladder carcinoma, it was expected that the expression of FAM83H and ZNF16 would be associated with standard prognostic variables." (PMID 32460791, 2020). "In human gallbladder carcinomas, immunohistochemical expression of FAM83H was significantly associated with ZNF16 expression." (PMID 32460791, 2020). "In this study, we demonstrate a positive correlation between immunohistochemical expression of FAM83H and ZNF16 in gallbladder cancers." (PMID 32460791, 2020). "Moreover, the co-expression patterns of nuclear FAM83H and nuclear ZNF16 were independent indicators of poor prognosis of gallbladder carcinoma patients." (PMID 32460791, 2020). "Furthermore, the nuclear expression of ZNF16 was indicated to be a potential prognostic factor of gallbladder carcinoma patients." (PMID 32460791, 2020). "Therefore, when considering the prognostic impact of FAM83H/ZNF16 expression in gallbladder carcinomas, further study is needed to find specific therapeutics targeting the FAM83H/ZNF16 pathway." (PMID 32460791, 2020). "This study investigated the expression of FAM83H and ZNF16 in 105 gallbladder carcinomas." (PMID 32460791, 2020). "Especially, MYC and the Wnt/β-catenin pathway might be a potential therapeutic targets of gallbladder carcinomas with high expression of FAM83H/ZNF16 because MYC is a transcriptional regulator of FAM83H and FAM83H stabilizes β-catenin." (PMID 32460791, 2020).
gallbladder carcinoma (continued). "The significance of the prognostic value of the expressions of FAM83H and ZNF16 in gallbladder carcinoma patients suggests that blocking of FAM83H-ZNF16 pathway might be a potential therapeutic target." (PMID 32460791, 2020). "Moreover, co-expression patterns of nuclear FAM83H and ZNF16 were also independent indicators of shorter survival of gallbladder carcinoma patients (overall survival; p < 0.001, relapse-free survival; p < 0.001)." (PMID 32460791, 2020). "Furthermore, we evaluated the prognostic significance of the individual and co-expression patterns of nuclear FAM83H and nuclear ZNF16 in 23 gallbladder carcinoma patients who received adjuvant chemotherapy." (PMID 32460791, 2020). "Therefore, based on the possible relationship between FAM83H and ZNF6 in cancers of hepatobiliary sites, we investigated the expressions and prognostic significance of FAM83H and ZNF16 in human gallbladder cancers." (PMID 32460791, 2020). "Therefore, further study of the mechanism(s) by which FAM83H/ZNF16 are involved in gallbladder cancer progression is needed." (PMID 32460791, 2020). "Therefore, our results suggest that FAM83H and ZNF16 are cooperatively involved in the progression of gallbladder cancers." (PMID 32460791, 2020). "Therefore, using established targeted therapeutic molecules which block cellular proliferation and invasiveness might be beneficial in the treatment of gallbladder carcinoma patients with tumors with high expression of FAM83H/ZNF16." (PMID 32460791, 2020). "Therefore, therapeutic agents which disrupt resistance to conventional anticancer therapy, such as PARP inhibitors, might be beneficial in the treatment of the poor prognostic subgroup of gallbladder carcinoma with high expression of FAM83H/ZNF16." (PMID 32460791, 2020). "However, studies on FAM83H and ZNF16 in gallbladder cancer have been limited." (PMID 32460791, 2020). "In SNU-308 gallbladder carcinoma cells, knock-down of FAM83H decreased ZNF16 expression and overexpression of FAM83H increased expression of ZNF16." (PMID 32460791, 2020). "Therefore, when considering our finding that there is a significant association between nuclear ZNF16-positivity and higher tumor stage and histologic grade, nuclear expression of ZNF16 might be significantly involved in the progression of gallbladder carcinomas." (PMID 32460791, 2020). "Therefore, FAM83H and ZNF16 might be potential therapeutic targets for gallbladder carcinoma patients, and the expression patterns of FAM83H and ZNF16 might be used as novel prognostic indicators for gallbladder carcinoma patients." (PMID 32460791, 2020). "Therefore, when considering the relationship between FAM83H/ZNF16 and tyrosine kinase- and BRAF-pathways, the inhibitors of the tyrosine kinase receptor and BRAF might be useful for the treatment of the poor prognostic subgroup of gallbladder carcinoma with high expression of FAM83H/ZNF16." (PMID 32460791, 2020). "Although there is no data for gallbladder cancers, a significant correlation between the expression of FAM83H and ZNF16 was seen in hepatobiliary cancers." (PMID 32460791, 2020).
leukemia (2 papers, 2020 to 2026). A malignant (clonal) hematologic disorder, involving hematopoietic stem cells and characterized by the presence of primitive or atypical myeloid or lymphoid cells in the bone marrow and the blood. "However, all studies on ZNF16 function at the cellular/molecular level have been performed in K652 leukemia cells or in cells expressing exogenous ZNF16." (PMID 41467516, 2026). "In addition, ZNF16 inhibited apoptosis and stimulated cell cycle progression by inhibiting INCA1 in K562 leukemia cells." (PMID 32460791, 2020).
tongue squamous cell carcinoma (2 papers, 2021 to 2026). A squamous cell carcinoma that arises from the tongue. "Genetic changes in ZNF16 have also been associated with tongue squamous cell carcinoma (TSCC), with 35% of TSCC samples having ZNF16 amplification and 5% missense mutations." (PMID 41467516, 2026).
breast carcinoma (1 paper, 2020). "Accessed 2 March 2020) indicates that higher expression of ZNF16 mRNA is an indicator of poor prognosis of liver cancer (Log-rank, p = 0.008) and breast cancer (Log-rank, p = 0.041)." (PMID 32460791, 2020).
cholangiocarcinoma (1 paper, 2020). A carcinoma that arises from the intrahepatic biliary tree (intrahepatic cholangiocarcinoma) or from the junction, or adjacent to the junction, of the right and left hepatic ducts (hilar cholangiocarcinoma). "The cBioPortal database (Accessed March 2, 2020) indicates that there is a significant correlation between the expression of mRNA of FAM83H and ZNF16 in cholangiocarcinoma (Spearman’s correlation, R = 0.70, p < 0.001)." (PMID 32460791, 2020). "In a search of the GEPIA database (Accessed May 2, 2020), mRNA expressions of FAM83H/ZNF16 was significantly associated with PARP1 mRNA expression in cholangiocarcinoma (FAM83H versus PARP1; Pearson correlation, R = 0.45, p = 0.005, ZNF16 versus PARP1; Pearson correlation, R = 0.34, p = 0.045)." (PMID 32460791, 2020).
colon cancer (1 paper, 2026). "Hct116 was included and DLD1 was omitted for simplicity, given that both are colon cancer cell lines and express similar levels of ZNF16." (PMID 41467516, 2026).
gastric cancer (1 paper, 2020). A primary or metastatic malignant neoplasm involving the stomach. "However, higher expression of ZNF16 mRNA was associated with favorable prognosis of head and neck cancer (Log-rank, p < 0.001) and gastric cancer (Log-rank, p = 0.017)." (PMID 32460791, 2020).
human papillomavirus infection (1 paper, 2026). "Additionally, RNA-sequencing experiments after ZNF16 depletion revealed that ZNF16 also has roles in a variety of pathways including extracellular matrix-receptor interaction, focal adhesions, cytokine-cytokine receptor interactions, human papillomavirus infection and cancer pathways." (PMID 41467516, 2026). "Pathway analysis using iPathwayGuide identified focal adhesion (FA), cytokine-cytokine receptor interaction (CCRI), extracellular matrix-receptor interaction (ECMRI), human papillomavirus infection (HPVI), and pathways in cancer (PC) as the top five pathways affected by ZNF16 depletion." (PMID 41467516, 2026).
lymph node metastasis (1 paper, 2020). "However, although not statistically significant, there is a tendency towards more positivity for FAM83/ZNF16 expression in patients with lymph node metastasis or distant metastasis." (PMID 32460791, 2020).
osteosarcoma (1 paper, 2026). A usually aggressive malignant bone-forming mesenchymal neoplasm, predominantly affecting adolescents and young adults. "Remarkably, there was a wide range of ZNF16 expression, with the osteosarcoma cell line U2OS having 30-fold higher expression than HeLa." (PMID 41467516, 2026).
pancreatic adenocarcinoma (1 paper, 2020). "In pancreatic adenocarcinoma, there was significant correlation between the expression of FAM83H mRNA and EGFR mRNA (Pearson correlation, R = 0.27, p < 0.001), and the expression of ZNF16 mRNA and EGFR mRNA (Pearson correlation, R = 0.33, p < 0.001)." (PMID 32460791, 2020).
squamous cell carcinoma (1 paper, 2020). A carcinoma arising from squamous epithelial cells. "In squamous cell carcinoma components, the expression of FAM83H and ZNF16 were detected in the cytoplasmic membrane, cytoplasm, and nuclei of tumor cells." (PMID 32460791, 2020).
tumor (5 papers, 2018 to 2026). "Further exploration of this role of ZNF16 will shed light on its association with tumor progression." (PMID 41467516, 2026). "Cytoplasmic expression of FAM83H was significantly associated with distant metastasis (p = 0.022), tumor stage (p = 0.040), histologic grade (p = 0.003), and the expression of nuclear ZNF16 (p = 0.019) and cytoplasmic ZNF16 (p = 0.009)." (PMID 32460791, 2020). "Cytoplasmic expression of ZNF16 was clearly associated with the age of the patients (p = 0.046), tumor stage (p = 0.003), and T category of the tumor stage (p < 0.001)." (PMID 32460791, 2020). "Positivity for nuclear ZNF16 was significantly associated with tumor stage (p = 0.028), T category of the tumor stage (p = 0.014), histologic grade (p < 0.001), and the cytoplasmic expression of ZNF16 (p < 0.001)." (PMID 32460791, 2020). "With regards to the subcellular localization of ZNF16, our results showed ZNF16 expression in both the cytoplasm and nuclei of tumor cells." (PMID 32460791, 2020). "Mutations in ZNF16 (zinc finger protein 16) were reported for the first time in malignancies, and it was shown that ZNF16 knockdown significantly diminished cell proliferation, migration, and invasion in vitro and tumor growth in vivo." (PMID 39613893, 2024). "Consistent with a role for ZNF16 in TSCC, ZNF16 depletion reduces TSCC cell viability and xenograft tumor size." (PMID 41467516, 2026).
cancer (3 papers, 2020 to 2026). A tumor composed of atypical neoplastic, often pleomorphic cells that invade other tissues. "Here, we describe a novel role for ZNF16 at the nucleolus and its association with changes in expression of a variety of genes involved in cancer pathways." (PMID 41467516, 2026). "ZNF16 (also called HZF1) is a C2H2 zinc finger protein that has been associated with cancer progression." (PMID 41467516, 2026). "Although no reports have investigated the relationship between FAM83H and ZNF16 in human cancers, we found a significant association between FAM83H and ZNF16 expression in human cancers in our search of the public database." (PMID 32460791, 2020). "In this study, we confirm the ubiquitous expression of ZNF16 in a variety of cancer and non-cancer cell lines and show that ZNF16 depletion reduces cell viability in all cell lines tested." (PMID 41467516, 2026). "Our research has confirmed that ZNF16 is expressed in different cancer and non-cancer cell lines and identified a novel role for ZNF16 at the nucleolus as a regulator of rDNA expression." (PMID 41467516, 2026). "In addition to the role of ZFN16 at the nucleolus, RNA-seq analysis after depletion of ZNF16 indicates that changes in ZNF16 levels impact gene expression of pathways involved in immune regulation and cancer." (PMID 41467516, 2026). "However, the reports concerning the role of ZNF16 in human cancers, especially with regards to the prognostic significance of ZNF16 expression in human cancers, is limited." (PMID 32460791, 2020). "Therefore, further study is needed to clarify the role of ZNF16 in the progression of human cancers." (PMID 32460791, 2020). "Therefore, further study is needed to clarify the relationship between FAM83H/ZNF16 expression and cancer progression." (PMID 32460791, 2020).
adenocarcinoma (1 paper, 2020). A common cancer characterized by the presence of malignant glandular cells. "The expression of FAM83H and ZNF16 were detected in both cytoplasmic and nuclear areas of adenocarcinoma components." (PMID 32460791, 2020).
ZNF16 also shares sentences with these, for which no sentence is quoted: prostate carcinoma (2 papers); colon adenocarcinoma (1); esophageal carcinoma (1); head and neck cancer (1); head and neck squamous cell carcinoma (1); hepatocellular carcinoma (1); liver cancer (1); lung carcinoma (1); metastatic tumor (1).